ZDHHC5 (zDHHC palmitoyltransferase 5)
Diseases named in the same sentence as ZDHHC5 in open-access papers (continued):
Sharing a sentence is not in itself a finding about the gene and the disease.
tumor (15 papers, 2017 to 2026). "In general, ZDHHC5 expression is associated with genes in tumor proliferation pathway." (PMID 36774350, 2023). "Therefore, we investigated ZDHHC5 for its potential association with tumor immunity and possible mechanism." (PMID 34621750, 2021). "Silencing ZDHHC5 reduced tumor growth in patient-derived organoids and xenografts, while Zdhhc5 ablation in mice inhibited CRC progression by reversing immunogenic ferroptosis suppression and alleviating PD-L1-mediated T cell inhibition." (PMID 42208545, 2026). "In cancer, ZDHHC5 palmitoylates oncogenic proteins, contributing to tumor progression and highlighting its relevance for cancer therapies." (PMID 40180214, 2025). "Recent studies have highlighted ZDHHC5’s diverse roles in the nervous system, tumor biology, and cardiac function." (PMID 40180214, 2025). "Bioluminescence imaging revealed that ZDHHC5 depletion significantly decreased tumor growth in mice following the injection of U251 and T98G cells." (PMID 38233791, 2024). "A study illustrated that knockdown of ZDHHC5 dramatically inhibited cell proliferation, colony formation and cell invasion in vitro, as well as severely hindered NSCLC tumor xenograft formation, demonstrating the oncogenic capacity of ZDHHC5." (PMID 36018061, 2023). "Pseudotime trajectory analysis of tumor cells shows that ZDHHC5 expresses in every branch suggesting that ZDHHC5 plays important roles in the whole differentiation process of tumor cells." (PMID 36774350, 2023). "Pharmacological blockade of ZDHHC5 with Lomitapide resulted in attenuated cancer cell growth and proliferation which significantly contributed to anti-tumor responses in vitro and in mouse model in vivo." (PMID 36774350, 2023). "As a result, we identified ZDHHC5 as a candidate gene expressing in most of the cell types in tumor sample compared to normal pancreas sample." (PMID 36774350, 2023). "ZDHHC5 can effectively maintain the proliferative activity of tumor cells and promote cell invasion and metastasis; therefore, increased expression of ZDHHC5 in LUAD tends to predict a poor prognosis." (PMID 37434393, 2023). "The results indicate that ZDHHC5-knockdown (Mia PaCa-2) tumor weight/volume is much smaller than those of Mia PaCa-2." (PMID 36774350, 2023). "In this study, we analyzed ZDHHC5 expression in immune subtypes and the correlation with the tumor microenvironment of LUAD." (PMID 34621750, 2021). "Understanding how ZDHHC5 modulates the tumor-immune interface could provide insights into combination therapies involving immune checkpoint inhibitors and ZDHHC5-targeted agents." (PMID 40180214, 2025). "Additionally, intracranial GBM xenografts were utilized to investigate the effects of genetically silencing ZDHHC5 on tumor growth." (PMID 38233791, 2024). "After propofol treatment, the palmitoylation level of EZH2 in tumor stem cells increased, which may be related to the increased palmitoyltransferase ZDHHC5 expression." (PMID 35927718, 2022). "For example, ZDHHC5 stimulates the proliferation and anchorage-dependent and anchorage-independent colony formation of non-small cell lung cancer cell lines and was found to be required in a subset of these cells for establishment of tumor xenografts in mice." (PMID 35927718, 2022). "ZDHHC5 was stained in over 75% of tumor cells, including medium and low expression LUADs." (PMID 34621750, 2021). "In addition to its role in tumor growth, ZDHHC5 also influences immune evasion in cancers." (PMID 40180214, 2025). "Moreover, we perform correlation analysis between ZDHHC5 and the proliferative genes and find that ZDHHC5 is significantly correlated with Akt, c-Raf, MEK and ERK in tumor cells." (PMID 36774350, 2023).
tumor (continued). "For non-tumor cells, ZDHHC5 is significantly correlated with Akt and c-Raf, but not with MEK and ERK." (PMID 36774350, 2023).
cancer (14 papers, 2021 to 2025). A tumor composed of atypical neoplastic, often pleomorphic cells that invade other tissues. "ZDHHC5 has been implicated in other cancers, while TMEM109 is involved in regulating apoptosis." (PMID 37756103, 2023). "While this review highlights ZDHHC5's involvement in neurodegenerative diseases, cancer, and cardiovascular disorders, it is true that direct evidence linking ZDHHC5 modulation to therapeutic outcomes is still limited." (PMID 40180214, 2025). "Understanding how ZDHHC5 modulates the function of substrates in cancer cells is therefore crucial for the development of targeted therapies." (PMID 40180214, 2025). "DHA, for example, significantly reduces fatty acid synthase (FASN) expression in cancer cells, inhibiting ZDHHC5 activity and promoting the degradation of PD-L1 via the CSN5-dependent ubiquitin-proteasome pathway." (PMID 40180214, 2025). "ZDHHC5, 9, 17, and 19 were significantly upregulated in the cancer pain model compared to the sham group." (PMID 38164190, 2024). "Pharmacological blockade of ZDHHC5 by Lomitapide results in reduced cancer cell growth and proliferation, which together contribute to antitumor effects in vitro and in vivo." (PMID 36774350, 2023). "We first check the expression level of ZDHHC5 in different cell lines and find that the expression level of ZDHHC5 is higher in cancer cells than that in HPDE cell." (PMID 36774350, 2023). "Pharmacological blockade of ZDHHC5 with Lomitapide results in attenuated cancer cell growth and proliferation which collectively contributes to antitumor effects in vitro and in vivo." (PMID 36774350, 2023). "In summary, we prove that pharmacological blockade of ZDHHC5 with Lomitapide resulted in attenuated cancer cell growth and proliferation." (PMID 36774350, 2023). "The mechanism is still unclear since there are few studies on ZDHHC5 at present and most of them are only reported to be related to cancer." (PMID 37163424, 2023). "Pharmacological blockade of ZDHHC5 with Lomitapide results in attenuated cancer cell growth and proliferation which collectively contributes to antitumor responses in vitro and in vivo." (PMID 36774350, 2023). "ZDHHC5 (Zinc finger DHHC-type containing 5) belongs to palmitoyl acyltransferases (PATs), which has been linked to the development of various cancers." (PMID 35927718, 2022). "However, the potential of ZDHHC5 as a prognostic biomarker for various cancers needs to be validated." (PMID 40180214, 2025). "In pancreatic cancer, ZDHHC5-mediated palmitoylation of SSTR5 enables cancer cell proliferation." (PMID 40977744, 2025). "For example, in cancer, identifying additional ZDHHC5 substrates could reveal novel therapeutic targets and deepen our understanding of its oncogenic role." (PMID 40180214, 2025). "Similarly, in cancer, ZDHHC5's role in palmitoylating oncogenic proteins like EZH2 and PD-1 suggests its potential as a therapeutic target." (PMID 40180214, 2025). "By mapping ZDHHC5 correlated genes and mRNAsi-based cancer stemness genes, we identified INCENP, a stemness gene, as the bridge between ZDHHC5 and CSCs in LUAD." (PMID 34621750, 2021). "We found that ZDHHC5, 9, 17, 19, and 23 were upregulated in the NCP model, indicating functional redundancy in the regulation of protein palmitoylation during cancer-induced pain or demonstrating the complexity of protein palmitoylation regulation in response to different stimuli." (PMID 38164190, 2024). "The small molecule caspase independent lethal 56 (CIL56) induces a unique form of nonapoptotic cancer cell death that is promoted by a complex formed between zDHHC palmitoyltransferase 5 (ZDHHC5) and an accessory protein, golgin A7 (GOLGA7, also known as GCP16)." (PMID 40930250, 2025).
cardiovascular disease (2 papers, 2023 to 2025). "In addition, it is known that ZDHHC5 is a palmitoyltransferase that modulates the activity of many proteins, some of them known cardiovascular disease-causing genes such as desmosomal cadherin desmoglein-2 (DSG2) and myelin regulatory factor (MYRF)." (PMID 37160609, 2023).
neurodegenerative disease (2 papers, 2025). A disorder of the central nervous system characterized by gradual and progressive loss of neural tissue and neurologic function. "Further research into the molecular mechanisms underlying ZDHHC5's functions in fatty acid metabolism will not only deepen our understanding of metabolic regulation but also open new avenues for therapeutic interventions in metabolic and neurodegenerative diseases." (PMID 40180214, 2025). "The palmitoyl acyltransferase zinc finger Asp-His-His-Cys motif-containing 5 (ZDHHC5) has garnered significant attention due to its roles in neurodegenerative diseases, oncogenesis, and cardiac function." (PMID 40180214, 2025). "However, the role of ZDHHC5 in the cross-talk between autophagy and neuroinflammation in neurodegenerative diseases is still unclear." (PMID 40180214, 2025). "Additionally, the development of specific inhibitors or activators of ZDHHC5 that can modulate its activity in neurons and microglia could provide new therapeutic strategies for neurodegenerative diseases." (PMID 40180214, 2025).
adenocarcinoma (1 paper, 2021). A common cancer characterized by the presence of malignant glandular cells. "Thus, we focused on the prognostic value of ZDHHC5 within adenocarcinoma, which should also be prospectively addressed." (PMID 34621750, 2021).
cardiac disease (1 paper, 2022). "Aside from information of zDHHC5 expression and palmitoylation, this study provides novel evidence that NCX1 palmitoylation is changed in cardiac disease in animal models and humans." (PMID 36277202, 2022). "In the present study, we provide novel evidence that zDHHC5 expression and palmitoylation are altered in cardiac disease, although this does not directly correlate with a change in the palmitoylation of its substrates NCX1 and PLM." (PMID 36277202, 2022).
ZDHHC5 also shares sentences with these, for which no sentence is quoted: esophageal squamous cell carcinoma (2 papers); fatty liver disease (2); infection (2); adenocarcinoma of the breast (1); astrocytoma of the brain (1); atherosclerosis (1); bipolar disorder (1); diabetes (1); epidermoid carcinoma (1); glioblastoma (1); Hepatic steatosis (1); hypertrophy (1); iron overload (1); ischemic stroke (1); left ventricular hypertrophy (1); lung papillary adenocarcinoma (1); metabolic disorders (1); multiple sclerosis (1); myocardial infarction (1); Obesity (1); osteoporosis (1); osteosarcoma (1); ovarian carcinoma (1); prostate adenocarcinoma (1); prostate carcinoma (1); psychiatric disorder (1); Sepsis (1); X-linked intellectual disability (1).